MYC (MYC proto-oncogene, bHLH transcription factor)
Diseases named in the same sentence as MYC in open-access papers (continued):
Sharing a sentence is not in itself a finding about the gene and the disease.
cancer (continued). "Furthermore, c-MYC potentially enhances the activation of SIRT1 by directly binding to the SIRT1 inhibitor Deleted in Breast Cancer 1 (DBC1) and blocking its interaction with SIRT1." (PMID 38397988, 2024). "In addition to protein-coding genes, several lncRNAs are transcriptionally activated by c-MYC in human cancers." (PMID 38886753, 2024). "Cancer Genome Atlas reports that c-MYC and its paralogs are involved in 28% of cancers." (PMID 39594704, 2024). "In cancer, MYC is one of the most frequently deregulated genes." (PMID 38674385, 2024). "Targeting the CDK9/ERK/MYC network in cancer cells, as well as their crosstalk with the TME via the complement system may yield improved responses in KRAS‐mutant patients." (PMID 39254172, 2024). "In most diseases described so far, and as seen in cancer, where deregulation of MYC is frequent, such excessive MYC activity drives various processes that then lead to pathologies due to the unfettered proliferation, changes in differentiation and altered metabolism, among others." (PMID 38510176, 2024). "This study highlights the intricate and complex nature of mitotic gene regulation in cancer cells marked by MYC amplification and provides a foundation for future studies to determine the exact mechanism by which N-MYC, WDR5, and PDPK1 converge on cell cycle related processes." (PMID 38605297, 2024). "Our findings reveal a cancer-promoting metabolic program is associated with alternative pre-mRNA splicing through JMJD6, providing a rationale to target JMJD6 as a therapeutic avenue for treating MYC-driven cancers." (PMID 38488852, 2024). "MYC has been one of the most appealing therapeutic targets for cancer drug development." (PMID 38200580, 2024). "The c-MYC oncogene is activated in over 70% of all human cancers." (PMID 38424045, 2024). "MYC activation was moderate, leading to similar expression levels as in cancer cells." (PMID 38471738, 2024). "CT1113 can reduce c‐MYC levels and inhibit USP28 and USP25 in various cancer cell lines, resulting in decreased expression of MYC–MAX target genes and increased ubiquitination of substrates like c‐MYC and Tankyrase, thus exhibiting a broad‐spectrum anticancer activity." (PMID 39678489, 2024). "MYC is the most prevalent oncogenic transcription factor involved in many cancers, including AML18." (PMID 38969699, 2024). "Also, an analysis of the TCGA database confirmed this observation as over 97% of MYC-upregulated cancers had coincreased PVT1 copy numbers." (PMID 38731892, 2024). "Patients with cancers driven by MYC signaling may benefit from therapies targeting these pathways, which could delay cancerous growth and recover antitumor immune responses." (PMID 37450923, 2024). "This review explores how MYC bridges these hallmarks by inducing metabolic reprogramming that influences an immunosuppressive microenvironment, and conversely, promoting immune evasive markers to influence immune cell and cancer cell metabolism." (PMID 38390324, 2024). "Key gene targets of MYC in cancer metabolism and oncoimmunology." (PMID 38390324, 2024). "MYC can demethylate the promoter of GS, prompting the synthesis of glutamine in cancer cells." (PMID 38218942, 2024).
cancer (continued). "Additionally, it is important to consider that aggressive cancers such as MYC-amplified Group 3 MB have a strong capacity to develop therapy evasion mechanisms and resistance when confronted with highly cytotoxic multimodal chemotherapy." (PMID 38184819, 2024). "Because of its involvement in carcinogenesis, MYC inactivation should reduce cancer cell survival." (PMID 39563886, 2024). "Gene translocation or amplification promotes MYC oncogenic activities in a number of human cancers." (PMID 38590645, 2024). "Importantly, c-MYC is the master gene responsible for the oncogenic activity of the Wnt/β-catenin pathway in the intestine, where APC mutations are sufficient for cancer initiation." (PMID 39065798, 2024). "Hence, lncRNAs can modulate MYC activity to control cancer cell invasion, and the function of GClnc1 in regulating MYC activity warrants further exploration." (PMID 37450923, 2024). "A80.2HCl interacts with CRBN and MYC, inducing MYC degradation at nanomolar concentrations, re-establishing the sensitivity of MYC-overexpressing cancer cells to CDK4/6 inhibitors and indicating the potential role of virtual screening for small-molecule degraders." (PMID 38791529, 2024). "However, MYC is by far the member of this family more heavily involved in cancer and is also the most ubiquitously expressed in human tissues." (PMID 39766110, 2024). "The MYC gene is known to be overactive in many types of cancer, and its inactivation could potentially slow down or stop the progression of the disease." (PMID 38195537, 2024). "In addition, MP1 shows synergistic anti-cancer efficacies with temsirolimus in MYC-driven MB cells by targeting the mTOR signaling pathway." (PMID 38200580, 2024). "Furthermore, mTORC1 not only regulates GLUD, but also actively controls GLS through S6K1-dependent c-MYC, enhancing cancer cells' uptake of glutamine." (PMID 38459595, 2024). "Moreover, beyond sustained proliferative signaling, MYC has roles in various other hallmarks of cancer mediated by its gene targets." (PMID 38390324, 2024). "Indeed, MYC is a well-known major driver of carcinogenesis and is one of the most commonly deregulated oncogenes identified in human cancers." (PMID 39031286, 2024). "The MYC oncogene is known to be overexpressed in many cancers and to be involved in tumorigenesis." (PMID 38731892, 2024). "Therapies aimed at inhibiting MYC expression and activity may potentially restore immune responses against human cancers." (PMID 38280005, 2024). "Therapeutically targeting MYC would have broad clinical impact across many types of human cancer." (PMID 38302473, 2024). "Reduction in MYC expression leads to down-regulation of known MYC targets, mRNA splicing and translation pathways, genes involved in cell division, proliferation, genomic instability, and hallmarks of cancer." (PMID 38315865, 2024). "Rapidly growing cancer cells naturally make more oncogenic MYC, which makes the genome less stable." (PMID 39563886, 2024). "We demonstrated that CREPT and MYC are co-expressed in several cancers." (PMID 39615685, 2024). "Cancers that show overexpression or dysregulation of the MYC oncogene are particularly prone to genomic instability due to the prominent effect that MYC has as an oncoprotein transcription factor in facilitating expression of genes needed for cell cycle phase progression and mitotic cell fate." (PMID 38605297, 2024). "In this study, we showed that dual inhibition of SUMOylation and MEK could conquer MYC-expressing KRAS-mutant cancers by complementarily enhancing DNA damage accumulation." (PMID 38992694, 2024).
cancer (continued). "Furthermore, triptolide has been investigated to modulate cancer gene expression via epigenetic downregulation of genes associated with super-enhancers (e.g., BRD4, MYC, RNA Pol II)." (PMID 39163135, 2024). "Overexpression of the proto-oncogene, MYC, was observed in dysplastic and cancer tissue, similar to a study of 47 CAC patients, where a higher rate of MYC amplification was reported compared to sporadic CRC, highlighting its importance to the CAC pathway, specifically." (PMID 38505585, 2024). "Can targeting MYC or lncRNAs advance the course of cancer immunotherapy?" (PMID 39075086, 2024). "Our findings indicate that dual inhibition of SUMOylation and MEK may be a promising treatment for MYC-expressing KRAS-mutant cancers by enhancing DNA damage accumulation." (PMID 38992694, 2024). "We found that MYC downregulation occurred via SUMOylation inhibition in KRAS-mutant cancer cells." (PMID 38992694, 2024). "MYC and PLK1 are major drivers of tumorigenesis, enhancing cancer cell growth and proliferation via autophagy and increased PLK1 levels are associated with poor cancer prognosis." (PMID 37450923, 2024). "One of the primary metabolic regulators that propels cancer is oncogenic MYC." (PMID 38892035, 2024). "Recently, a gene signature that correlated with MYC expression and was significantly enriched in ribosome biogenesis and RNA metabolism genes was identified in MYC-driven cancer, further confirming the importance of ribosomal regulation in MYC-specific oncogenic properties." (PMID 38715059, 2024). "MYC is a key oncogenic protein in human cancer but remains a difficult protein to target directly." (PMID 38302473, 2024). "Conversely, we found no loss of ERBB2, EGFR, ABL1, RELA, and RELB transcript in c-MYC-destabilized cells compared to controls, and the 3′UTRMYC1-18-treated cancer cells tended to restore MYC expression towards the normal female mammary epithelial expression levels." (PMID 39123391, 2024). "It has been suggested that, under these aberrant conditions, MYC could function as a global amplifier increasing the output at all active promoters, leading to hypertranscription in cancer cells." (PMID 38321218, 2024). "Current research on MYC primarily focuses on its role in cancer." (PMID 39188714, 2024). "Therefore, C-MYC was shown to be oncogenic in a reprogramming process, and the activation of an MYC-dependent cancer enhancer was demonstrated to cause genetic mutations in human mammary epithelial cells." (PMID 38791215, 2024). "In cancer, on the other hand, MYC is frequently deregulated through different mechanisms including aberrant signal transduction leading to increased MYC transcription or increased MYC mRNA and protein stability, amplifications, chromosomal translocations, and altered enhancer activity." (PMID 39031286, 2024). "In this study, the authors identify genome-wide MYC synthetic-lethal interactions that could serve as potential alternative targets for the treatment of MYC-driven cancers." (PMID 38302473, 2024). "Abrogating MYC oncogenic function was one of targeted therapies for cancer." (PMID 38566153, 2024). "Prior studies have interrogated the function of KAT2A in MYC-driven cancer." (PMID 38820154, 2024). "Our study shows that derepression of FAXDC2 is also a key consequence of Wnt inhibition, suggesting that FAXDC2 may be as important a Wnt target as MYC in Wnt-high cancers." (PMID 38488003, 2024). "MYC gene overexpression can sometimes sensitize cancer cells to BCL-2 inhibitor-induced apoptosis." (PMID 38756697, 2024).
cancer (continued). "We also discuss the multifunctional capacity of MYC in various cellular cancer processes, including its influences on immune response, metabolism, cell cycle, apoptosis, autophagy, pyroptosis, metastasis, angiogenesis, multidrug resistance, and intestinal flora." (PMID 37450923, 2024). "Finally, given the link between c-MYC and cancer stemness, we identified that NCAPG2 was positively correlated with PCa CSC properties." (PMID 38166947, 2024). "This suggests that the cell death observed may be a direct effect of the MYC inhibitor on the cancer cells alone." (PMID 39766097, 2024). "This assay showed high protein synthesis activity in control solvent-treated cells and strong inhibition of protein synthesis by MP1 and cycloheximide in both cell lines, suggesting the anti-cancer potential of MP1 is partly based on targeting the MYC/mTOR-driven protein synthesis pathway." (PMID 38200580, 2024). "Furthermore, signals released by the cancer cells themselves, such as aberrant activation of the pro-oncogene K-Ras and overexpression of MYC protein genes, also play crucial roles in generating a deeply immunosuppressive environment for PAAD." (PMID 38375157, 2024). "Furthermore, RNA interference experiments in this study confirmed the upregulation of NBS1 expression by endogenous c-MYC in kidney epithelial cell lines (293T) and in the HeLa cancer line." (PMID 39594704, 2024). "These constitute many of the Hallmarks of Cancer and, as MYC may impinge on all these programs, it is a common target for oncogenic activation." (PMID 38510176, 2024). "MYC is an oncogene that is highly expressed in cancer cells." (PMID 39126109, 2024). "Given such a prominent role of MYC in cancer metabolism, we next wanted to see whether MP1 modulates overall metabolism in a representative MYC-amplified HD-MB03 cell line." (PMID 38200580, 2024). "SLC1A5 has long been a focus of investigation in cancer pathophysiology, where it is noted to be upregulated in numerous cancer cell lines by metabolic transcriptional regulators such as c-MYC and the kinase mTOR, which governs cancer cell proliferation, growth, and survival." (PMID 38792190, 2024). "Moreover, MYC also enables cancer cells to evade and suppress immune surveillance to protect their survival through the following several different mechanisms." (PMID 39135122, 2024). "Thus, inhibiting MYC in cancer cells is expected to potentiate immune-mediated recognition and elimination." (PMID 39766097, 2024). "Dysregulated pre-mRNA splicing and metabolism are two hallmarks of MYC-driven cancers." (PMID 38488852, 2024). "Indeed, although its expression is tightly regulated in normal cells, cancer cells are almost unavoidably characterised by deregulated MYC activity." (PMID 38510176, 2024). "MYC signaling, while amplified in cancer cells, is also essential to normal cell function." (PMID 39093942, 2024). "An improved perspective of the MYC–SNF5 interaction indicates that SNF5 deletion in tumours, particularly in malignant rhabdoid tumour (MRT), leads to uncontrolled MYC activity with the help of SNF5 depleted SWI/SNF complex and describes how MYC target genes are upregulated in SNF5-deleted cancers." (PMID 39471843, 2024). "Despite its prominent role in cancer pathogenesis, MYC overexpression alone cannot mediate cellular proliferation or neoplastic transformation, rather, MYC overexpression affects normal cells in a highly destructive manner, resulting in cell death, senescence, and/or proliferative arrest." (PMID 37450923, 2024). "Thus, while both N-MYC and c-MYC repress multiple components of cancer-intrinsic innate immune signaling, they do so via different mechanisms." (PMID 38748789, 2024). "The pVEC-ASO3 targets UBA2 mRNA, a hallmark cancer pathology in MYC-driven cancer, while pVEC-ASO4 has no complementary sequences." (PMID 38391508, 2024).
cancer (continued). "In cancer, polyamine metabolism is frequently dysregulated, and multiple oncogenic pathways could result in upregulated polyamine synthesis, such as MYC, RAS-RAF-MEK-ERK, and PTEN-PI3K-mTORC1 signalling." (PMID 38504107, 2024). "MYC is overexpressed and contributes to many different cancers as an oncogene." (PMID 38225354, 2024). "Since MYC is a common oncogene in a wide variety of cancers, the strategy of MYC inhibition by MP1 might also be useful in other MYC-addicted cancers." (PMID 38200580, 2024). "The cancer cell lines are responsive to the MYC inhibitor treatment dose and time, dependently." (PMID 39766097, 2024). "Targeting MYC is among the highest priorities for cancer therapeutics." (PMID 37450923, 2024). "Instead of directly targeting c-MYC, modulating the expression of genes interacting with c-MYC may represent a novel strategy in cancer treatment." (PMID 39513905, 2024). "MYC interacts with BPTF to induce MDR in cancer cells through upregulation of ABC transporters." (PMID 37450923, 2024). "At the same time, due to the difficult-to-target biological characteristics of MYC, targeting the downstream targets of MYC to form a synthetic lethal strategy may be more effective in this subtype of cancer patients." (PMID 38638876, 2024). "Interestingly, a large-scale analysis of mutations in women's cancers (breast, ovarian, endometrial, and cervical) revealed a high mutation frequency (19%) in NDRG1, second only to MYC (22%)." (PMID 38987777, 2024). "Additionally, phosphatase and tensin homolog (PTEN), a commonly mutated, deleted, or silenced tumor suppressor in numerous cancers, has been linked to the WWP1-PTEN axis in MYC-induced tumorigenesis and progression." (PMID 39949609, 2024). "Furthermore, MYC drives transcription of oncogenic splicing factors that alter splicing decisions in cancer cells and promote oncogenic pathways." (PMID 38413979, 2024). "In addition to its role in the DDR, USP28 was also demonstrated to stabilize the c-MYC oncogene by antagonizing its ubiquitin-mediated degradation by the ubiquitin ligase FBW7 that is frequently lost in cancers." (PMID 39398482, 2024). "Whether CHMP5 also regulates AML, in which the BRD4-dependent MYC super-enhancer is also a therapeutic vulnerability, and other cancers that display a p300-BRD4 dependency remains to be determined." (PMID 38352301, 2024). "Moreover, our previous findings on the MYC-HIF-2alpha stemness pathway are supported by the evidences from other studies on human cancer." (PMID 39963656, 2024). "Moreover, considering the significant roles MYC holds in cancer development, the present study discusses effective direct or indirect therapeutic strategies to combat MYC-driven cancer progression." (PMID 38390324, 2024). "A key target in cancer therapy, MYC comprises three homologous genes - C-MYC, N-MYC and L-MYC." (PMID 38637125, 2024). "Amplification of the MYC gene is a common occurrence in different types of human cancers." (PMID 38302631, 2024). "It is well established that BRD4 regulates transcription of MYC in cancer." (PMID 38256018, 2024). "Assessing the MYC expression in cultured non-neoplastic sebaceous tissue was not possible, and we, therefore, focused on comparing the expression in our SebCA cells to established cancer lines in which MYC was known to be highly expressed and functionally significant." (PMID 39337668, 2024). "Specifically inspecting cancer cells with MCR loss, we observed that in the vast majority of cells, the copy-number estimate of the MCR regions were low whereas the expression level of MYC was increased." (PMID 38877600, 2024). "The development of c-MYC inhibitors has always been an elusive goal in the field of cancer therapy." (PMID 38240704, 2024). "Besides TRA2B gene amplification, increased levels of the ETS-1 and c-MYC transcription factors have been proposed as possible mechanisms to explain TRA2B upregulation in cancer cells." (PMID 38448406, 2024).